SRF (serum response factor)
Diseases named in the same sentence as SRF in open-access papers (continued):
Sharing a sentence is not in itself a finding about the gene and the disease.
cardiomyopathy (15 papers, 2013 to 2025). A disease of the heart muscle or myocardium proper. "Together, these data identify impaired SRF transcriptional activity in iCIR2KO and iCIRS12KO hearts, which likely contributes to loss of sarcomeric structure leading to fatal cardiomyopathy in both models investigated." (PMID 36125265, 2022). "Therefore, we wondered whether MRTF-A altered localization due to increased phospho(T25)-cofilin-1 expression might cause impaired SRF activity in LMNA-induced cardiomyopathy." (PMID 36550158, 2022). "Precise regulation of SRF expression is critical for mesoderm and cardiac crescent formation in the embryo, and altered SRF levels lead to cardiomyopathies." (PMID 41234403, 2025). "Previously, our group has shown that increased levels of SRF in transgenic mouse line carrying human SRF under control of the Myh6 promoter resulted in cardiomyopathy and early mortality." (PMID 40164849, 2025). "Our results showed that cardiac specific SRF overexpression reduced the lifespan of mice and induced cardiomyopathy." (PMID 40164849, 2025). "The precise regulation of SRF expression is critical for mesoderm formation and cardiac crescent formation in the embryo, and altered SRF levels lead to cardiomyopathies in the adult heart, suggesting its vital role in cardiac development and disease." (PMID 36769235, 2023). "Together, these results show that the expression of cofilin-1 phosphorylated on T25 affects SRF-mediated gene expression and leads to cardiomyopathy." (PMID 36550158, 2022). "In MHC-CELFΔ males, where the phenotype is only partially penetrant, both alternative splicing changes and down-regulation of inhibitors of SRF correlate with the development of cardiomyopathy." (PMID 23437181, 2013). "In addition, at 6 months of age, SRF-Tg mice showed cardiomyopathy with increased heart size, increased heart weight, and four-chamber dilatation." (PMID 40164849, 2025). "Similarly, SRF cleavage by enteroviral protease 2A has also been predicted to play a role in cardiomyopathy." (PMID 35681202, 2022). "Inhibition of the MRTF-A/SRF axis promotes the development of cardiomyopathy and heart failure." (PMID 36550158, 2022). "Precise regulation of SRF expression is critical for mesoderm formation and cardiac crescent formation in the embryo, and altered SRF levels lead to cardiomyopathies in the adult heart, suggesting the vital role played by SRF in cardiac development and disease." (PMID 35681202, 2022). "Among the multiple signaling pathways investigated over the last decades that are involved in cardiomyocyte hypertrophy and cardiomyopathy pathogenesis, induction of the cardiomyocyte hypertrophic gene program via the master transcription factor-serum response factor (SRF) is of crucial importance." (PMID 33142804, 2020). "Previous studies in mice have indicated the relevance of SRF in the development of cardiomyopathy." (PMID 29206857, 2017). "Increased levels of SRF in the heart is known to cause robust activation of SRF signaling, and in the absence of other stimuli, SRF upregulation is sufficient to cause cardiomyopathy." (PMID 28886070, 2017). "Here, we show that in muscle cells carrying a cardiomyopathy-causing LMNA mutation, phospho(T25)-cofilin-1 binds to myocardin-related transcription factor A (MRTF-A) in the cytoplasm, thus preventing the stimulation of serum response factor (SRF) in the nucleus." (PMID 36550158, 2022). "Considering the important role of SRF and MEF2C in the progression of cardiomyopathy, a subnetwork under their regulation was constructed and the biological functions they may affect were also indicated." (PMID 25338953, 2014). "A subnetwork under the regulation of SRF and MEF2C was also constructed and the functions they may affect were also indicated considering the considerable evidence in support of their involvement in cardiomyopathy." (PMID 25338953, 2014).
atherosclerosis (14 papers, 2015 to 2025). A disease characterized by the build-up of fatty material and calcium deposition in the arterial wall resulting in partial or complete occlusion of the arterial lumen. "Knowing that atherosclerosis and intimal injury are characterized by high levels of ROS and that ROS regulate SRF, it can be assumed that ROS are potentially implicated in the SRF-induced suppression of VSMC differentiation markers." (PMID 33233489, 2020). "This is because suppression of myocardin and MRTF activities causes SMC proliferation, especially in atherosclerosis and restenosis, suggesting the importance of SRF/myocardin as a sensor under mechanical stress and growth factor signaling to regulate such phenotypic switches in SMCs." (PMID 32885587, 2021). "As such, deficiency in the transcription of these SRF‐dependent genes can cause various diseases of the cardiovascular system including congenital heart and vascular defects and other cardiomyopathy such as hypertrophy, heart failure, atherosclerosis, and restenosis." (PMID 32885587, 2021). "One SRF transcriptional target is nexilin, an F-actin–binding protein, which was also downregulated in atherosclerosis datasets." (PMID 41246212, 2025). "In the context of atherosclerosis, SRF plays the opposite role by attenuating the expression of contractile markers genes, and promoting VSMC dedifferentiation." (PMID 33233489, 2020). "Since dysregulation of SRF and NIK has been implicated in many inflammatory diseases including hypertension, restenosis, atherosclerosis, aneurysms and cancer, the role of SM22 in the pathogenesis of these diseases warrants further investigation." (PMID 29284006, 2017). "Our data reveal links among SP1, miR-320a, SRF and miR-1/miR-133a in endothelial dysfunction in atherosclerosis." (PMID 25728840, 2015). "In addition to SRF and nexilin, many of the other YAP/TAZ–TEAD targets were likewise downregulated in atherosclerosis datasets, reinforcing the notion that YAP/TAZ deficiency recapitulates disease-associated transcriptional reprogramming." (PMID 41246212, 2025). "Disruption of the SRF–myocardin axis has been mechanistically linked to VSMC phenotypic switching that contributes to fibrous cap thinning, extracellular matrix degradation, and heightened plaque vulnerability in atherosclerosis." (PMID 41246212, 2025). "MiR-1, miR-133a and other targets of SRF may contribute to the development of atherosclerosis and CAD." (PMID 25728840, 2015). "LMOD1, another target gene of MYOCD/SRF that falls with increasing age, was uncovered in genome wide association studies for coronary artery disease, raising the possibility LMOD1 depletion may play a role for the age-dependence of atherosclerosis." (PMID 40081573, 2025). "Compatible with these findings, the target genes SRF (serum response factor), arrestin beta ARRB, and interleukin 1 receptor associated kinase IRAK4 showed upregulation after treatment suggesting that tRFs play a role in processes that leads to atherosclerosis." (PMID 40305238, 2025). "In atherosclerosis, DNA methylation can regulate a variety of genes that define VSMC phenotypic transformation, such as serum response factor (SRF), PDGF-B, and TAGLN." (PMID 35399657, 2022). "MRTF/SRF signaling plays a key role in phenotypic modulation of SMCs, such as in atherosclerosis and neointima formation where the expression of MRTF/SRF target genes is reduced." (PMID 30158653, 2018). "TET2, through its role in DNA demethylation, potentially influences the expression of important vascular smooth muscle cell genes such as myocardin (MYOCD) and serum response factor (SRF), which are crucial for smooth muscle function and differentiation in atherosclerosis." (PMID 40428388, 2025). "Additionally, CARMN interacts with serum response factor (SRF) to regulate VSMC plasticity, significantly impacting the progression of atherosclerosis." (PMID 38597937, 2024).
Hypertension (13 papers, 2015 to 2025). The presence of chronic increased pressure in the systemic arterial system. "Additionally, the DNA sequence around rs604723, a hypertension-associated polymorphism, matches the serum response factor (SRF) binding site." (PMID 33919522, 2021). "For instance, myocardin - a coactivator of the serum response factor (SRF) becomes inactivated upon exposure to hypertension or biomechanical stretch and this attenuates the expression of gene products belonging to the contractile apparatus." (PMID 30190682, 2018). "ROCK is a novel mediator modulating aortic VSMC stiffness through SRF/myocardin signaling which offers a therapeutic target to reduce aortic stiffening in hypertension." (PMID 29169155, 2017). "In addition to modulating vascular contraction in hypertension, ROCK activation is associated with increased vascular stiffness through processes that increase SRF/myocardin signalling." (PMID 29394331, 2018). "We here hypothesized that Rho kinase (ROCK) acts as a novel mediator that regulates intrinsic VSMC mechanical properties through the serum response factor (SRF)/myocardin pathway and consequently regulates aortic stiffness and blood pressure in hypertension." (PMID 29169155, 2017). "Activation of the serum response factor (SRF)/myocardin transcription pathway is responsible for increased SMC stiffness and thereby plays a central role in hypertension-mediated aortic stiffening." (PMID 28912461, 2017). "Selective inhibition downstream of ROCK signaling, e.g., by targeting SRF/myocardin as with CCG-100602, provides a new avenue to the development of safer therapies by specifically targeting the pathological alterations of hypertension while minimizing off-target effects." (PMID 29169155, 2017). "In addition, our most recent study demonstrated that serum response factor (SRF)/myocardin pathway acts as a pivotal mediator of aortic VSMC stiffening and plays a central role in the pathological aortic stiffening in hypertension." (PMID 29169155, 2017).
dilated cardiomyopathy (10 papers, 2012 to 2022). Cardiomyopathy which is characterized by dilation and contractile dysfunction of the left and right ventricles. "Deregulation of MRTF-A/SRF pathway has been described in mice and cells expressing dilated cardiomyopathy (DCM)-causing lamin A/C mutations." (PMID 35145145, 2022). "The depletion of SRF in the adult mouse heart leads to severe dilated cardiomyopathy associated with the down-regulation of target genes encoding sarcomeric proteins including α-cardiac actin." (PMID 35806398, 2022). "In summary, we show for the first time an actin-microtubule cytoskeletal interplay mediated by cofilin-1 and MRTF-A/SRF, promoting the dilated cardiomyopathy caused by LMNA mutations." (PMID 36550158, 2022). "In addition, it was demonstrated that cardiac-specific deletion of SRF in the embryonic heart results in cardiac defects and deletion of SRF from the adult heart caused reduced contractility leading to dilated cardiomyopathy." (PMID 22815879, 2012). "In fact, SRF hyperexpression can lead to pathological hypertrophy, while inhibition of SRF activity can result in development of dilated cardiomyopathy." (PMID 22666593, 2012). "Thus, it is likely the combined effects of dysregulation of SRF and alternative splicing that ultimately determine the extent to which contractile function in the heart is disrupted and dilated cardiomyopathy ensues." (PMID 23437181, 2013).
liver cancer (10 papers, 2012 to 2025). An epithelial or non-epithelial malignant neoplasm that arises from the liver. "Meanwhile, IGF2BP1 promotes the growth of tumor cells such as liver cancer by enhancing the expression of a variety of serum response factor (SRF) target genes, including PDLIM7, FOXK1, MKI67 and MYC." (PMID 38166832, 2024). "As a m6A reader, IGF2BP1 stabilizes mRNA such as SRF to promote cell growth and invasion in ovarian and liver cancer." (PMID 35346372, 2022). "The researchers additionally reported that ATO can inhibit stem cell proliferation and metabolism of liver cancer cells by targeting the SRF/MCM7 complex." (PMID 34413873, 2021). "Arsenic trioxide has been shown to suppress liver cancer cells metastasis by targeting the SRF/MCM7 complex." (PMID 34277436, 2021). "IGF2BP1 is upregulated in ovarian, skin, lung, and liver cancers, and enhances the expression of serum response factor (SRF) by elevating m6A modification, thereby accelerating cell proliferation and metastasis." (PMID 32709063, 2020). "Overexpression of SRF promotes the growth and migration of liver cancer cell lines and promotes a mesenchymal phenotype, a feature that has been associated with the resistance of cancer cells to EGFR inhibitors." (PMID 23115635, 2012). "Furthermore, the tumor targeting of FA-SRF-BSANPs (Ctumor/Cblood, 0.666 ± 0.053) was significantly higher than those of SRF-BSANPs (Ctumor/Cblood, 0.560 ± 0.083) and sorafenib-solution (Ctumor/Cblood, 0.410 ± 0.038) in nude mice with liver cancer." (PMID 30744448, 2019).
liver fibrosis (10 papers, 2015 to 2025). "A deeper understanding of integrin–MRTF/SRF signaling in liver fibrosis will aid in the development of more effective targeted therapies aimed at halting fibrotic progression." (PMID 39996739, 2025). "In one study, it is reported that HSC-conditional SRF knockout mice demonstrated a similar phenotype of liver fibrosis compared to wild-type mice fed identical diets." (PMID 34067715, 2021). "Mechanistically, HOTTIP can function as a regulator of SRF expression through miR‐150 binding, which provides an intriguing approach for treating liver fibrosis." (PMID 30548190, 2019). "In summary, our experimental data suggest that HOTTIP can serve as the endogenous sponge to bind miR‐150 and then release its target SRF, thereby promoting the progression of liver fibrosis." (PMID 30548190, 2019). "More importantly, introduction of miR-122 into CCl4-treated mice attenuated the expression of FN1 and SRF in fibrotic livers, and alleviate hepatic fibrosis in vivo." (PMID 25909171, 2015). "In addition, SRF promotes liver fibrosis by inducing the transcriptional activation of NCF1/NCF2 to promote ROS production." (PMID 40045169, 2025). "Further study showed that miR‐150 and SRF are involved in the profibrogenic effect of HOTTIP, which implies that targeting the HOTTIP‐miR‐150‐SRF axis may signify a new therapeutic application in liver fibrosis." (PMID 30548190, 2019). "All these data suggest that FN1 and SRF are bona fide targets of miR-122, and miR-122 may suppress hepatic fibrosis by simultaneously blocking multiple aspects of fibrogenesis, including collagen production, fibril assembly and ECM contraction." (PMID 25909171, 2015). "This study discloses a novel TGF-β-miR-122-FN1/SRF signaling cascade and further identifies the importance of miR-122 in preventing hepatic fibrogenesis and therefore substantially extends our understanding about the function of miR-122 and the molecular mechanisms of hepatic fibrosis." (PMID 25909171, 2015). "This study suggest that SRF integrates transcriptional activation of NCF1/NCF2 and ROS production to promote liver fibrosis." (PMID 34067715, 2021). "Finally, conditional SRF deletion in HSCs attenuated both bile duct ligation (BDL)- and CCl4-induced liver fibrosis in mice." (PMID 39996739, 2025). "In conclusion, these results suggest that FA combined with BMSC treatment can induce greater release of miR-19b-3p, which inhibits the activation of HSCs by suppressing the RhoA/ROCK1/SRF and RhoA/ROCK1/LIMK1 pathways, contributing to alleviation of liver fibrosis." (PMID 35721175, 2022).
lung carcinoma (10 papers, 2013 to 2025). "In agreement, IGF2BP1 expression showed the most significant and conserved association with elevated SRF expression in ovarian, skin, liver and lung cancer, as determined by Pearson correlation of RNA-sequencing data available via the TCGA." (PMID 30371874, 2019). "RhoA and SRF also control the expression of several drug resistance and metastasis-associated genes in EGFR-mutant lung cancer cells." (PMID 36509758, 2022). "Their expression is associated with an overall poor survival probability in ovarian, liver and lung cancer supporting the notion that SRF/IGF2BP1-enhanced gene expression is a conserved driver of oncogenesis that promotes both tumor growth and metastasis." (PMID 30371874, 2019). "Since we have previously reported the pro-invasive role of hMENAΔv6 in lung cancer cells, we silenced SRF and found the abrogation of this hMENAΔv6 function in A549 cells." (PMID 29907768, 2018). "This leads to the stabilization of SRF mRNA, ultimately increasing lung cancer cell proliferation." (PMID 40584294, 2025). "Consistently, 35 SRF/IGF2BP1-dependent genes showing conserved association with SRF and IGF2BP1 expression indicate a poor overall survival probability in ovarian, liver and lung cancer." (PMID 30371874, 2019). "Recent studies indicate that serum response factor (SRF) is highly expressed in tumors such as hepatocellular, thyroid, esophageal and lung carcinoma." (PMID 23426188, 2013).
ovarian carcinoma (7 papers, 2015 to 2023). A malignant neoplasm originating from the surface ovarian epithelium. "Mechanistically, MBZ was shown to inhibit multiple cancer-associated signaling pathways including ELK/SRF, NFKB, MYC/MAX, and E2F/DP1 in cisplatin-resistant ovarian cancer cells." (PMID 34232919, 2021). "For example, IGF2BP1, a positive-reader that enhances mRNA stability and storage, promotes the expression of oncogene SRF in an m6A-dependent manner in ovarian cancer." (PMID 32998774, 2020). "Hence, the obtained results revealed the contribution of SMAD 7 and SRF in anti-migratory as well as anti-proliferative effects of the compound tested in the SKOV-3 ovarian cancer cell line." (PMID 32046103, 2020). "Several other Igf2bp1 target RNAs (SRF, cMyc, and CD44) are reduced in lung and ovarian carcinoma cells incubated with the compound." (PMID 34895045, 2022). "Mechanistically, MBZ was revealed to inhibit multiple cancer-related signal pathways including ELK/SRF, NFKB, MYC/MAX, and E2F/DP1 in cisplatin-resistant ovarian cancer cells." (PMID 34232919, 2021). "Mechanistically, MBZ was shown to inhibit multiple cancer-related signal pathways including ELK/SRF, NFKB, MYC/MAX, and E2F/DP1 in cisplatin-resistant ovarian cancer cells." (PMID 34232919, 2021). "We showed that DMU-214 down-regulated SRF mRNA and protein levels in the SKOV-3 ovarian cancer cell line." (PMID 32046103, 2020). "Monensin was shown to target multiple cancer-related signaling pathways such as Elk1/SRF, AP1, NFκB and STAT, and suppresses EGFR expression in ovarian cancer cells." (PMID 26639992, 2015). "Monensin suppresses multiple cancer-related pathways including Elk1/SRF, AP1, NFκB and STAT, and reduces EGFR expression in ovarian cancer cells." (PMID 26639992, 2015). "Because miRNA3652 is downregulated in ovarian cancer cells, several signalling cascades, including the WNT—catenin signalling route, the MRTF-SRF pathway, and the Hedgehog signalling system, are stimulated, leading to the overexpression of the GL2, SRF, and VCAN genes." (PMID 37845675, 2023). "In ovarian cancer, elevated expression of the ‘oncogenic gene set’ comprising IGF2BP1, SRF, FOXK1 and PDLIM7 was not significantly (P = 0.077) associated with poor overall survival (OS) but showed the expected trend with a HR of 1.22." (PMID 30371874, 2019). "Monensin was shown to target multiple cancer-related signaling pathways including Elk1/SRF, AP1, NFκB and STAT, and suppress the expression of EGFR, but not IGF-1R, in ovarian cancer cells." (PMID 26639992, 2015).